CXCL10 (C-X-C motif chemokine ligand 10)
Diseases named in the same sentence as CXCL10 in open-access papers (continued):
Sharing a sentence is not in itself a finding about the gene and the disease.
tumor (continued). "Indeed, Th1-secreted IFN-γ was shown to trigger a cytotoxic activity of tumor-associated macrophages (TAMs) and also induces CXCL9/MIG and CXCL10/IP-10 secretion by macrophages, which may affect the tumor progression by angiogenesis inhibition." (PMID 29780381, 2018). "Indeed, evidence in patients with ovarian cancer demonstrated that the increased expression of CXCL9 and CXCL10 correlates with an increased number of tumor-infiltrating CTL and a high CD8+/regulatory T cells ratio that lead to a reduction in cancer metastasis and to a better prognosis." (PMID 30319638, 2018). "In addition, exogenous application of the CXCR3 ligand CXCL10 to tumor tissues, or ectopic expression of CXCL10 by tumor cells, has been demonstrated to increase the number of tumor-infiltrating NK cells expressing CXCR3 and to prolong NK cell-dependent survival in mice." (PMID 29088306, 2017). "Moreover, the higher amounts of the CXCL10 chemokine released by irradiated BC cells in vitro may further contribute to the tumor infiltration by T cells observed after SBRT." (PMID 29163540, 2017). "We also observed increased amounts of the CXCL10 chemokine (even if with high variability among experiments; p-value not significant), able to recruit immune effectors as T lymphocytes, NK cells, and dendritic cells in the tumor microenvironment, in MDA-MB453 and MCF7 models after three doses of RT." (PMID 29163540, 2017). "Thus, it is possible that during cancer progression production of CXCL10 by transformed epithelial cells might stimulate tumor metastasis." (PMID 28567040, 2017). "This hypothesis is supported by previous findings that show CXCL10 as a potent angiostatic factor, which inhibit a number of angiogenic activities, including human tumor-derived angiogenesis that can induce the dissociation of newly formed blood vessels even in the presence of angiogenic factors." (PMID 28376104, 2017). "However, the specific source of CXCL10 in tumor-bearing mice needs to be determined." (PMID 27764779, 2016). "Analysis of immune mediator expression in Pan02 tumours at day 29 revealed that αCD40 significantly upregulated the Th1 chemokine CXCL10 at the mRNA and protein level in Pan02 tumours, along with IL-2, perhaps explaining the expansion or increased infiltration of tumour CD8+ T cells." (PMID 26918344, 2016). "This marked sensitivity of the immune C26 tumor microenvironment to corticosterone was also reflected by the correlation between anti-IL-6-induced decreased plasma levels of the hormone and increased mRNA levels of Cxcl9, Cxcl10, and Cxcl11 in food-restricted pre-cachectic C26-bearing mice." (PMID 27829137, 2016). "Moreover, in RCC, pervious studies found the expression of CXCL9, CXCL10 and CXCL11 increased in tumor compared to normal kidney tissues, suggesting the association with TILs and favorable prognosis, and the promotion of tumor specific immunity in systemic high-dose interleukin-2 (IL-2) therapy." (PMID 26910919, 2016). "However, the source of CXCL10 in tumor-bearing mice need a further study." (PMID 27782173, 2016). "Indeed immunohistochemical analyses confirmed the presence of CXCL10 within the tumour mass." (PMID 25495686, 2015). "However, the neutralizing antibodies for CCL5 or CXCL10 significantly hampered the migration induced by tumor supernatant (pCCL5 < 0.05; pCXCL10 < 0.01), and the migration of T lymphocytes was further inhibited by the combined use of anti-CCL5 and anti-CXCL10 neutralizing antibodies (p < 0.001)." (PMID 26317795, 2015). "Moreover, IL-17-producing αβ T cells stimulate the release of several cytokines (such as IL-6, IL-12, CXCL9, and CXCL10) by immune or cancer cells, leading to DC maturation or effector T cell recruitment to the tumor, and as a consequence, to an increase of the anti-tumor immunity." (PMID 25538706, 2014).
tumor (continued). "Therapy with CXCL10 is effective in reducing the rate of tumor growth, whereas it fails to induce tumor complete regression, which suggests that further treatment may require supplemental combination therapies that directly target tumor cells." (PMID 24816916, 2014). "IP-10 (CXCL10) induces lymphocytic infiltration; and may act in a paracrine manner by affecting tumor microenvironment and in an autocrine manner by acting on tumor cells and may play a role in tumor invasiveness and progression." (PMID 24265713, 2013). "However, CXCL10 was more strongly positive in tumor samples of vaccinated mice." (PMID 21067607, 2010). "Hence, an increase in IFN-γ at the tumour site of CCL19-treated mice could explain the relative increases in CXCL10/IP-10 and CXCL9/MIG." (PMID 16598185, 2006). "Our study demonstrated that CXCL10+ macrophages and the CXCR3+ T cells were critical mediators of the systemic anti-tumor immunity induced by cryoablation in advanced NSCLC." (PMID 41818612, 2026). "The role of CXCL10 has been extensively elucidated in tumors beyond NPC, with current evidence suggesting that it induces a favorable anti-tumor TIME." (PMID 41399390, 2026). "In various tumors, the CXCL10/CXCR3 axis has also been found to regulate the migration, differentiation, and activation of immune cells, thereby inhibiting tumor growth." (PMID 41399390, 2026). "Concurrently, GNL3 functions as a corepressor of immune-responsive genes such as CXCL10 and TAP1 via class I histone deacetylases (HDACs), thereby facilitating CD8+ T cell elimination and establishing an immunosuppressive tumor microenvironment." (PMID 41772945, 2026). "For example, CXCL9 and CXCL10 recruit effector T cells into the tumor via CXCR319, 20, promoting anti-tumor responses, while CCL2 recruits MDSCs through CCR2, thereby inhibiting immune responses." (PMID 41399390, 2026). "Tumours can also act more indirectly, for example by suppressing the production of chemo-attractants such as CXCL9 and CXCL10, which thereby limits the migration of T-cells into the tumour microenvironment 64,65." (PMID 40768308, 2025). "Consistently, mRNA expression analysis of subcutaneous tumor tissues derived from CT26 cell injections showed analogous upregulation of PD-L1, CCL5, CXCL9, and CXCL10." (PMID 40959109, 2025). "Based on this evidence, we select CXCL10, CXCL11, and IFNG as rational proof-of-concept candidates for proposing a gene-therapeutic approach that remodels the TME by inducing tumour-intrinsic expression of immunostimulatory cytokines." (PMID 41366257, 2025). "In group 0, several immune checkpoint and pro-inflammatory genes, including PDCD1LG2 (PD-L2), CD274 (PD-L1), HLA-A, CXCL10, and CD163, displayed relatively high expression, suggesting a more inflamed tumor microenvironment." (PMID 41517303, 2025). "In contrast, in pancreatic, colon or glioblastoma tumors, CXCL10 can activate alternative signaling pathways such as STAT3, which promotes immunosuppression, or PI3K/Akt, which supports tumor cell proliferation and resistance to apoptosis." (PMID 40760734, 2025). "Activated tumor-infiltrating eosinophils produce high levels of chemokines, such as CCL5, CXCL9, and CXCL10, which attract co-metastatic CD8 + T cells to the tumor, leading to tumor rejection and prolonged survival." (PMID 39141277, 2025). "This inhibition promotes the secretion of immune-modulatory factors CXCL10, CXCL11, EBI3, and FLT3LG by tumor cells, thereby alleviating immunosuppression and enhancing CD8+ T cell recruitment into the tumor microenvironment and boosting antitumor immunity." (PMID 41293150, 2025). "We also observed higher mRNA expression levels of the CXCR3 ligand genes CXCL9 and CXCL10 in TLS-positive as compared to TLS-negative tumors, suggesting the recruitment of CD8 + T cells into tumor mass." (PMID 40319321, 2025).
tumor (continued). "CXCL10 promotes epithelial-mesenchymal transition and recruits CXCR3+ regulatory T cells (Tregs), thereby contributing to an immunosuppressive tumor microenvironment." (PMID 40919170, 2025). "Nevertheless, while CCL5 became a more dominant ligand for CCR5 in the KPC-4545 tumor, CCL4 remained a dominant ligand for CCR5 and CXCL12, CXCL10, and CXCL16 arose as major ligands for different receptors in the KPC-3403 model following anti-IL-1β treatment." (PMID 39948655, 2025). "CXCR3 ligands, such as CXCL9, CXCL10, and CXCL11, are mainly produced by monocytes, endothelial cells, and tumour cells and are crucial for regulating anti-tumour immunity." (PMID 40361472, 2025). "Ruxolitinib, a selective JAK1/2 kinase inhibitor known to suppress JAK-STAT signaling, was used to assess the role of tumor-intrinsic IFN signaling in the elevated release of ICAM-1 and CXCL10." (PMID 40861475, 2025). "This dual activation enhances the immunostimulatory milieu, as seen in reduced tumor proliferation (via Ki67 staining) and increased cytokine production (e.g., CCL5, CXCL10, TNFα) in syngeneic models." (PMID 41029427, 2025). "CXCL9 and CXCL10 are induced by IFN-γ secreted from activated T cells and establish chemotactic gradients to recruit CXCR3+ CD8+ T cells to tumor niches." (PMID 40698080, 2025). "In this study, we described the role and molecular mechanism of oHSV in inducing TLS formation in tumours, and identified that oHSV therapy recruits stem‐like TCF1+CD8+ T cells via CXCL10/CXCR3 pathway to propagated TLS formation." (PMID 39219056, 2025). "In ‎cancers where CXCL10 inhibits angiogenesis and metastasis, targeting the CXCL10/CXCR3 ‎axis is a promising strategy to effectively ‎suppress tumor growth." (PMID 40760734, 2025). "Multiple tumor models demonstrate that RT induces the release of chemokines such as CXCL9, CXCL10, and CXCL11, which enhance T-cell trafficking." (PMID 39881333, 2025). "RT triggers the release of chemokines (CXCL10 and CXCL16) from tumor cells to recruit effector T cells to the tumor site, thereby enhancing the anti-tumor immune response." (PMID 40141437, 2025). "For instance, CXCR3, a receptor for chemokines CXCL9, CXCL10, and CXCL11, is more highly expressed in tumor tissues than in normal tissues." (PMID 39940842, 2025). "In a humanized mouse model, these synNotch T cells significantly inhibited tumor growth, increased CD3+ T cell infiltration, and elevated CXCL10 and IFN-gamma levels at the tumor site." (PMID 40308611, 2025). "In NSCLC, ALKBH5 expression within tumor cells enhances the secretion of CCL2 and CXCL10, thereby recruiting PD-L1 + TAMs and promoting macrophage polarization toward the M2 phenotype." (PMID 40176140, 2025). "It increases PD-L1 expression on tumor cells but activates the cGAS/STING pathway, triggering cytokine production (e.g., CCL5, CXCL10) that recruits and activates CD8+ T cells." (PMID 39949780, 2025). "For example, in tumor cells, the m6A writers METTL3 and METTL14 suppress the expression of chemokines CXCL9 and CXCL10, leading to immune exclusion." (PMID 40176140, 2025). "Remarkably, DNA-methylation–induced silencing of immune effector genes was shown to impair T-cell trafficking to the tumor site by reducing tumor cell secretion CXCL9 and CXCL10." (PMID 39867570, 2025). "Similarly, modulation of MAPK/ERK signaling in conjunction with CXCL10 expression patterns could help reduce inflammation-driven tumor progression or support T-cell infiltration, depending on the immunological profile of the tumor." (PMID 40760734, 2025). "The effects of the CXCL9/CXCL10/CXCL11-CXCR3 axis can vary, even within the same organ, depending on the distribution of CXCR3 subtypes in tumor cells." (PMID 40362215, 2025). "Among these, the key secretory molecules, IFN-γ, CXCL10, IL-4, VEGF, and TNF-α, are mainly involved in angiogenesis and tumor progression." (PMID 41029387, 2025).
tumor (continued). "This is characterized by enhanced expression of pro-inflammatory cytokines such as IFN-γ, which can also stimulate the secretion of chemokines (e.g. CXCL9, CXCL10, and CXCL11) to amplify the anti-tumour immune response." (PMID 40510180, 2025). "When compared to the combined treatment group, both CXCL10 expression and CD8+ T cell infiltration are lower in the Yoda 1 treatment group, due to the less death of tumor cells after Yoda 1 treatment." (PMID 40583158, 2025). "Both poly-I:C and rintatolimod activate TLR3-mediated nuclear translocation of TRAF3 and IRF3, leading to type-1 interferon production and CXCL10 expression, which attract CD8+ T cells for anti-tumor immunity." (PMID 39949780, 2025). "The interplay of the tumor-derived molecules like immune checkpoint ligands (PD-L1 and PD-L2), chemokines (CXCL9, CXCL10, and CXCL12), along with cytokines (TGF-β and IL-10), creates a complex immunosuppressive environment in EwS." (PMID 40242222, 2025). "The proposed KMPAG signature underscores the importance of three genes—CLEC4A, CXCL10, and LAT2—in modulating tumor–immune crosstalk and predicting patient outcomes." (PMID 40607411, 2025). "We first investigated the effects of genetically targeting Ackr2 on the release by tumor cells of two chemokines, CCL5 and CXCL10, which can be scavenged by ACKR27 and have high affinity for this receptor." (PMID 40248897, 2025). "Inhibition of CXCL10 can therefore impair immune cell trafficking, reduce IFN-γ-mediated immune activation and ultimately suppress anti-tumor immunity." (PMID 40760734, 2025). "CXCL10 and ICAM1 are essential for T cell trafficking and adhesion, which are critical for effective tumor localization and infiltration." (PMID 41293181, 2025). "This CXCL10 surge correlated with extravasation of CXCR3+CD8+ T cells, leading to greater tumor shrinkage and improved survival." (PMID 40311102, 2025). "Like CXCL10 and CXCL11, CCL3 and CCL4 have been attributed both tumor-promoting and anti-tumor effects." (PMID 40895532, 2025). "MSC-derived chemokines CXCL9, CXCL10, and CCL5 interact with CXCR3 and CCR5 on NK cells to promote their directed migration into tumor tissues." (PMID 40643499, 2025). "This conclusion is also supported by a corresponding increase in the ligands for CXCR3, CCR5 (e.g., CXCL9, CXCL10, CCL5) in both tumor and liver supernatants after treatment, whereas CXCR6 ligand (CXCL16) is higher only in the tumor." (PMID 41415437, 2025). "This trend was similarly observed at the protein level, as Western blot results indicated significant upregulation of CXCL10, CXCL11, OAS2, MTIE, and MTIX in tumor tissues, although FAT1 exhibited an opposite trend compared to the qPCR results." (PMID 40574841, 2025). "Recently, it was shown that the protease DPP4 reduces the infiltration of lymphocytes by cleaving and inactivating CCL5 and CXCL10 and that the inhibition of DPP4 improves tumour control and synergises with immune checkpoint therapies (ICBs)." (PMID 40579444, 2025). "qRT-PCR revealed significant upregulation of CXCL10, CXCL11, ME1, MT1X, FAT1, OAS2, and MT2A in tumor tissues compared to normal tissues." (PMID 40574841, 2025). "The mosaic COUP-TFII induction experiments suggest that iCoup autonomously induces EC expression of CXCL10, a chemokine that attracts T cells expressing CXCR3, which also proved necessary for the enhanced T cell recruitment and tumor inhibition." (PMID 40796746, 2025). "By pairing systemic neutralization with therapies that specifically induce local CXCL10 production (such as oncolytic viruses or localized radiotherapy ), clinicians could artificially generate a steep chemotactic gradient that strongly favors immune infiltration to the primary tumor site." (PMID 41516196, 2025). "Within the TME, eosinophils activated by TNF-α and IFN-γ release chemokines such as CXCL9 and CXCL10, promoting CD4+ and CD8+ T cell infiltration and enhancing anti-tumor immune responses." (PMID 41200171, 2025).
tumor (continued). "Specifically, the expressions of CXCL10, ICMA1, IL18, ITGAL, SOCS3, and TLR3 were higher in tumor tissues compared to their corresponding paracancerous tissues." (PMID 40838069, 2025). "OVs effectively promote T-cell infiltration into the TME through genetic engineering to express chemokines (e.g., CXCL10, CCL5) or by disrupting physical tumor barriers, thereby enhancing anti-tumor immune responses." (PMID 41425703, 2025). "The cytokine analysis of LLC and MC38 tumor cell lines revealed substantial expression of CCL2 and CXCL10, as observed previously." (PMID 39566333, 2025). "A recent elegant study showed that immune evasion in ARID1A mutant tumours is mediated by impaired chromatin accessibility of IFNγ responsive genes, including Th1 chemokines CXCL9, CXCL10 and CXCL11." (PMID 39920335, 2025). "In line with these spatial and mechanistic insights, CXCL10-high tumors are significantly more infiltrated by all T cell subtypes, but with the highest fold-change for CTL density within tumor cell nests." (PMID 40497965, 2025). "MTAP-deficient cancer cells showed impaired induction of key chemokines, CXCL9, CXCL10, and CXCL11, particularly in response to immune cell interaction, thereby contributing to the development of an immunosuppressive “cold” tumor microenvironment." (PMID 41246302, 2025). "Considering the individual loadings on PC2 and PA, we found that patients who engaged in moderate PA had lower levels of CXCL9, CXCL10, and CXCL11, known pro-inflammatory chemokines involved in immune cell migration and tumor progression." (PMID 40510182, 2025). "VB-85247 also induced the IFN-dependent chemokines CXCL10 (IP-10) and CCL5, which are known to be important for the recruitment of immune effector cells into the tumor microenvironment." (PMID 39700406, 2025). "We found that CRTC1 overexpression in tumor cells upregulates PD-L1, suppresses IFN-γ and IL-2 production, reduces CXCL10/11 secretion, and impairs T-cell cytotoxicity." (PMID 40977688, 2025). "Further analysis showed increased production of proinflammatory interleukins such as IL‐1β and IL‐16 and accumulation of various chemotactic agents, including CCL3, CCL4, CCL5, CXCL9, CXCL10, and CXCL11, in the tumor tissue." (PMID 41221154, 2025). "The tumor microenvironment in this subtype features elevated levels of IFN-γ, CXCL9, and CXCL10, alongside notable infiltration of CD8+/CD4+ T cells." (PMID 40260289, 2025). "Our data suggest that PTE remodels the tumor microenvironment (TME) by activating STING-mediated signaling, leading to increased chemokine production (e.g., CXCL10, CCL5) and enhanced CD8+ T-cell recruitment and function." (PMID 41181138, 2025). "M1 macrophages promote tumor destruction by directly killing tumor cells and by enhancing the recruitment and activation of cytotoxic CD8+ T cells and natural killer (NK) cells via secretion of CXCL9, CXCL10, and CXCL11 chemokines." (PMID 40475782, 2025). "The upregulation of chemokine genes Ccl3, Ccl5, Cxcl9, and Cxcl10 suggests that these activated CD8+ T cells possess increased migratory capacity, allowing them to infiltrate the tumor microenvironment more effectively." (PMID 40534857, 2025). "Beyond direct tumor clearance, CAR-Ms secreted T cell-recruiting chemokines (e.g., Cxcl10), facilitated antigen presentation to amplify T cell priming, and reprogrammed immunosuppressive myeloid populations toward an immunostimulatory M1 phenotype." (PMID 41388305, 2025). "ELISA analyses revealed that CXCL10 and CCL5 expression levels in tumor tissues were significantly lower in BIN1-KO mice compared to BIN1-WT mice." (PMID 40346580, 2025). "The homing of activated tumour antigen‐specific CD8+ T cells to the tumour microenvironment (TME) is mediated by chemokines CXCL9 and CXCL10 that are produced, among other cells, by tumour‐resident cDC1." (PMID 40878038, 2025).